IGFBP3 (insulin like growth factor binding protein 3)
Diseases named in the same sentence as IGFBP3 in open-access papers (continued):
Sharing a sentence is not in itself a finding about the gene and the disease.
tumor (continued). "Although some studies indicated the tissue expression of IGFBP‐2 but not IGFBP‐3 has a tumor suppressor effect and it is a chemosensitivity marker in UC." (PMID 35368130, 2022). "This significant negative correlation was also detected between IGFBP3 levels and the size of the tumor." (PMID 34858769, 2021). "The miR-21 targets include the genespromoting apoptosis (PDCD4 and LRRFIP1), as well as the tumor suppressor genes inhibitinginvasion (RECK and TIMP3) and proliferation(IGFBP3).Furthermore, miR-21 can affect microglial behavior, thus ensuring favorableconditions for tumor growth." (PMID 34707896, 2021). "Understanding of the mechanisms whereby the TβR‐V mediates growth inhibition (tumor suppressor) signaling stimulated by IGFBP‐3 and TGF‐β should be important to elucidate the molecular basis of IGFBP‐3 and TGF‐β actions and to understand their roles in human cancers." (PMID 34485840, 2021). "In the transplantation with/without low IGFBP3 expression, a continuous expression of HIF-2α allows the tumor to escape from the growth arrest caused by hypoxia." (PMID 34824343, 2021). "This significant negative correlation was also detected between IGFBP3 levels and the size of the tumor (r=−0.808, p <0.01)." (PMID 34858769, 2021). "In contrast, other players of the GH-IGF system, such as insulin-like growth factor binding protein 3 (IGFBP3) and IGF-II receptors, inhibit mitogenesis, stimulate apoptosis and modulate IGF-I actions, thus acting as protective factors against tumor progression." (PMID 34304361, 2021). "Furthermore, insulin-like growth factor-binding protein 3 (IGFBP3) has shown an altered glycosylation pattern in serum and tumor cell membrane samples isolated from CRC patients." (PMID 34070747, 2021). "A significant negative correlation was also detected between IGFBP3 levels and the size of the tumor." (PMID 34858769, 2021). "We demonstrate for the first time that the expression of the genes CA9, NDUFA4L2, EGLN3, BHLHE41, IGFBP3, and ANGPTL4, regulated by HIF1, is largely correlated, and along with VWF, the expression levels of these genes during tumor progression decreased coordinately." (PMID 34046336, 2021). "IGFBP3 was known to exert insulin-like growth factor (IGF)-independent effects to inhibit cell proliferation and migration, and enhance apoptosis in many malignant tumor cells." (PMID 33931579, 2021). "Additionally, MDSCs in EC TME can be recruited and activated by cancer cell-derived cytokines/chemokines (IL-6, IGFBP-3, CXCL16, and GM-CSF), thereby accelerating tumor progression by inhibiting CD8+ T cell activation." (PMID 33995371, 2021). "Specifically, our analysis of patient specimens implied that overall survival was worse for those patients whose tumours are GRP78-negative/IGFBP-3-positive than for those with GRP78-negative/IGFBP-3 negative tumours." (PMID 33352865, 2020). "Insulin-like growth factor-binding protein-3 IGFBP-3 is a tumor suppressor gene, independent of IGF signaling." (PMID 32710395, 2020). "Our findings indicate that tumour IGFBP-3 expression can be exploited to predict responses to chemoradiotherapy and that IGFBP-3 may represent a novel prognostic factor." (PMID 32093285, 2020). "Increased expression of IGFBP3 inhibits the growth of metastatic cells in the lungs, but does not inhibit the growth of primary tumor cells and normal kidney cells." (PMID 31936274, 2020). "Tumor cells derived from KrasG12D/+; p53f/f; Ng2/Cspg4+/+, and KrasG12D/+; p53f/f; Ng2/Cspg4f/f mice were treated with IGFII followed by real-time PCR analysis for Igfbp3 expression." (PMID 29196603, 2018). "There may well be inter‐racial heterogeneity in tumor grades or serum levels of IGF‐1, IGFBP‐3, or testosterone, and therefore external validation of our findings using a larger cohort is warranted." (PMID 29992746, 2018).
tumor (continued). "Our studies over several years have shown that IGFBP-3 stimulates an oncogenic pathway in which the activation of SphK 1, leading to increased sphingosine-1-phosphate generation, results in the transactivation of EGFR which drives tumor proliferation." (PMID 29623068, 2018). "On the contrary, in some studies, IGF1 mRNA expression was higher—but IGFBP3 mRNA expression was lower—when tumor tissues were compared to that of adjacent nontumor tissue." (PMID 29702590, 2018). "However, some changes were observed in the levels of expression of binding protein genes, with a decrease in IGFBP2, IGFBP3, and IGFBP4 expression and an increase in IGFBP7 expression with tumor progression." (PMID 28882129, 2017). "The TIF secretome was, for the most part, distinctly different from the plasma secretome, although some factors such as TIMP-1, IGFBP-1, PTX3, uPA and IGFBP-3 were observed in both TIF and plasma and may provide plasma biomarkers of the tumor secretome." (PMID 27995973, 2016). "We propose that tumor cells in CSF express IGF1R, but IGFBP3 prevents IGF1 from being bioavailable." (PMID 27255663, 2016). "To identify if IGFBP3 is required for tumor growth and lymphatic metastasis, we generated 3 LN1–1 subclones that stably express 2 different IGFBP3 shRNA and one control vector (pLKO-GFP) to access the effects of IGFBP3 silencing in LN1–1 cells." (PMID 26540630, 2015). "Especially, IGFBP-3 and IGFBP-5 show their tumor suppressor character in HNSCC." (PMID 25880247, 2015). "In the last group an increase of GH-IGF1 axis (evaluated as circulating IGF1 and IGFBP3) was observed without any change in tumour-free survival rates and median tumour-free survival time." (PMID 25225571, 2014). "Our data suggest that IGFBP3 and EGFR may share a common transcriptional hub or factory, and disruption of these interactions could play a role in tumor progression." (PMID 24019942, 2013). "Additional factors may include crosstalk between IGFBP3 and EGFR signaling pathways and tumor heterogeneity." (PMID 24019942, 2013). "Thus, it is intriguing to speculate that restoring IGFBP3 expression and/or use of demethylating drugs could contribute to new therapeutic strategies for HB, especially with the existence of additional epigenetically silenced genes in this tumor type, such as HHIP, RASSF1, SOCS1, APC and CASP8." (PMID 22401581, 2012). "The results of Western blotting analysis also indicated that the levels of IGFBP-3 in CAFs and NAFs were not correlated to fibroblast-mediated tumor growth." (PMID 21249190, 2011). "Because we observed IGFBP3 expression in GIST in response to imatinib, we hypothesized that IGFBP3 would mediate its anti-tumor effects." (PMID 19903356, 2009). "Methylation of IGFBP3 was detected in significantly more tumours with Gleason score ⩾7, than ⩽6 (P=0.01), but was not significantly correlated with TNM classification or PSA level." (PMID 17453001, 2007). "As IGFBP-3 functions downstream of many growth suppressors and its growth suppression effects are drastic, and as it is a small-sized secreted protein, the use of IGFBP-3 in tumor therapy will be a promising option." (PMID 15661074, 2005). "Nevertheless, one specific IGF-binding protein known to be produced in excess by some tumour types (e.g. colorectum, prostate) is IGFBP-2, and this may lead to some increase in circulating levels (which are much lower than those of IGF-I and IGFBP-3)." (PMID 14583772, 2003). "Among malignant epithelial subpopulations, IGFBP3+Epi (IGFBP3-expressing epithelial cells) and LHX9+Epi (LHX9-expressing epithelial cells) had elevated glycolysis levels, which correlated with poor prognosis, immune suppression, and changes in the tumor microenvironment." (PMID 40115255, 2025). "Importantly, “IGFBP3 Targeting Therapy” efficiently suppresses GBM invasion in vitro and tumor growth in vivo via reducing PD-L1 expression, suggesting that IGFBP3 may be a potential novel target for GBM therapy." (PMID 38326861, 2024).
tumor (continued). "The pivotal function of IGFBP3 in the insulin signaling axis may account for its regulatory role, representing a novel contributory mechanism to the tumor suppressor effect of ULK2 that is independent of its involvement in autophagy control." (PMID 38952983, 2024). "IGFBP3 encrypts a protein with an IGFBP domain and a thyroglobulin type-I domain and forms a ternary complex with insulin-like growth factor acid-labile subunit, which plays a prominent role in tumor proliferation suppression and apoptosis induction (Rajah, Valentinis & Cohen, 1997)." (PMID 37397026, 2023). "Silencing of IGFBP-3 expression by promoter hypermethylation in cisplatin-treated tumor cells was reported previously to activate the PI3K/AKT pathway via de-repression of IGF-1R signaling, decreasing tumor cell sensitivity to cisplatin in NSCLC and inducing cisplatin-resistance in NSCLC patients." (PMID 36766747, 2023). "On the other hand, the value of serum IGFBP3 in tumor prognosis should not be ignored." (PMID 36409444, 2022). "Furthermore, many of these genes are tumor suppressors, such as GATA4 and IGFBP3/5, and may contribute to the therapeutic effect of PRC2 inhibition in tumor." (PMID 35169119, 2022). "Another experiment identified a role for IGFBP3 in the growth of oesophageal squamous cell carcinoma cells with high CD44 expression by suppressing ROS production through an IGF-independent mechanism in the hypoxic tumour microenvironment and ultimately exerts tumour-promoting activities 37,38." (PMID 34512163, 2021). "At the initial stage of tumor development, the activation of the genes under consideration provides adaptation to hypoxia, accompanied by a metabolic shift, i.e., the development of glycolysis and a decrease in oxidative phosphorylation (EGLN3, NDUFA4L2, ANGPTL4, CA9, and, apparently, IGFBP3)." (PMID 34046336, 2021). "IGFBP3 could inhibit angiogenesis by upregulating THBS1, leading to tumor growth arrest." (PMID 34824343, 2021). "The expression of HIF-2α persisted in growing tumor cells without IGFBP3 (P4-pBIG2i group)." (PMID 34824343, 2021). "Studies have shown that IGFBP-3 participates in the repair of DSB damage through NHEJ, responds to DNA-destructive chemotherapy, and forms a nuclear complex with EGFR and DNA-PKCs, promotes the stability of tumor cell genome and leads to the migration and invasion of tumor cells." (PMID 32653017, 2020). "IGF-1/IGFBP-3 ratio has been shown to positively correlate with free IGF-1 and has been associated with a number of clinical outcomes, including functional status in nonagenarians, metabolic disease, and neoplastic diseases." (PMID 32492897, 2020). "In summary, we found that circRNA hsa-circ-0046263, which was upregulated in NPC tissues and NPC cell lines, could sponge miR-133a-5p, upregulated the expression of downstream targets gene IGFBP3, and promoted NPC cell migration, invasion, and tumor metastasis." (PMID 32703944, 2020). "This suggests that IGFBP-3 may either utilize multiple mechanisms for its anti-tumor actions depending upon the cellular environment or the observed IGFBP-3 interaction with cytoplasmic/nuclear partners may not represent major IGFBP-3 anti-tumor signaling." (PMID 32443727, 2020). "One molecular reason for this may be the expression levels of IGFBP in PaSCs: Tumor PaSCs have lower expression levels of IGFBP-3 and higher expression levels of IGFBP-2 compared to the normal PaSCs." (PMID 29475434, 2018).
tumor (continued). "The in vivo-specific down-regulation of FOXM1 suggests that ZR30 has the ability to alter the tumor micro-environmental cue to which the transcription of FOXM1 indirectly responds, which may result in a lower expression of IGFBP3 comparing to control, due to a less hypoxic environment." (PMID 29290950, 2017). "Since IGFBP-3 is the main circulating carrier of the IGFs, as well as a regulator of local IGF bioavailability, the absence of IGFBP-3 may affect the access of IGF-1 to cells within the tumor microenvironment." (PMID 27448965, 2016). "IGFBP-3 may also enhance tumor cell proliferation independent of its IGF-binding capacity, for example in response to EGF receptor signaling by increasing sphingosine kinase activity." (PMID 27448965, 2016). "Therefore neither cell proliferation nor apoptosis appears to account for different tumor growth rates in response to HFD or IGFBP-3 deletion." (PMID 27448965, 2016). "Compared to the 10 proteins (GM-CSF, IGFBP-1, IGFBP-3, PTX-3, PDGF-AA, serpin E1, PEDF, TIMP-1, TIMP-4 and uPA) detected in the plasma of MDA-MD-231_WT tumor bearing mice, only 2 (serpin E1 and TIMP-1) were detected in the plasma of MCF-7_WT tumor bearing mice." (PMID 27995973, 2016). "There may be multiple factors that can influence IGFBP-3 expression, and its expression may have both positive and negative effects on tumor development." (PMID 27144338, 2016). "Additionally, most (69%, 57/83) specimens demonstrated higher IGFBP3 staining intensity in tumor nests as compared to their corresponding non-tumor epithelia." (PMID 26540630, 2015). "In patients with NSCLC, the greatest activation of IGF-1R was observed in tumours that expressed high levels of IGFBP-3, although it is not clear whether this activation was ligand dependent." (PMID 25866791, 2015). "By contrast, the over-expressed genes in the networks may trigger tumorigenesis of HNSCC by altering gene expression associated with inflammatory, proliferation, apoptosis and other processes, such as IL6, IGFBP3, ELF3, and PTGES in the both subgroups of tumor cells." (PMID 24069219, 2013). "Surprisingly, loss of IGFIR increased both the mRNA level, and to a greater extent, the protein level of IGFBP3, further suggesting that the elevated IGFBP3 might be capable of suppressing tumor growth in the absence of IGFIR." (PMID 24260413, 2013). "Since IGFBP-3 sequesters IGF-I from circulation, the decreased levels of IGFBP-3 that result from the translocation may increase the bioavailability of IGF-I, thus promoting tumor growth." (PMID 23383402, 2013). "However, at the protein level, there was up-regulation of CXCL5/ENA78, CCL20/MIP3-α, IGFBP3, OPN and TIMP1 in tumours and their PN, indicating that these could be early events in the gastric tumorigenesis." (PMID 21092330, 2010). "Thus, it is possible that IGFBP3 further modulates the viability of GIST cells or alters their response to imatinib by targeting endothelial cells or other important cell types, such as macrophages, in the tumor microenvironment." (PMID 19903356, 2009). "The frequency of IGFBP3 methylation in HGPIN was not statistically different from tumour (P=0.383)." (PMID 17453001, 2007). "We therefore postulate that the tumor suppressor role of IGFBP-3 will not be limited to HCCs." (PMID 15661074, 2005). "It is conceivable that Igfbp3 might interact with proteins that are sensitive to matrix stiffness, such as FAK and LOX, both of which serve as potentially crucial regulators of gene expression in cancer, influencing cell function and shaping the surrounding tumor microenvironment." (PMID 37653219, 2023). "Knockdown of IGF1 and IGFBP3 expression level via applying a CRISPR/Cas9 genome editing system could promote apoptosis in OS cells which in turn leading to downregulating the expression level of ROS and Nrf-2, and thereby enhancing the sensitivity of Graphene Oxide in tumor cells." (PMID 33768092, 2021).
tumor (continued). "High-fat feeding may, therefore, enhance tumor growth in the absence of IGFBP-3." (PMID 27448965, 2016). "Significant correlations were recorded between MEG3 and anatomical site, SIRT1 and tumor stage, and miR-27a/IGFBP3 and LN metastasis among obese CRC patients, while IGF1 was correlated with tumor stage and LN metastasis among non-obese CRC patients." (PMID 38704452, 2024). "PRM analysis for peptides from IGFBP3 and MAGEA1 showed probable or definite presence in material from patients without a tumour." (PMID 36185575, 2022). "The results showed that the levels of APN, IGF-1, and IGFBP-3 are not significantly different between PTC, FTC, and MTC but that the ratio of IGF-1/APN and IGF-1/(APN×IGFBP-3) ratio is independently related to tumor size." (PMID 33815885, 2021). "Both IGFBP-3 and IGFBP-7 levels were relatively stable between the preoperative and 1-year postoperative samples, regardless of tumor characteristics and treatments." (PMID 33767994, 2021). "It has been shown that activation of IGFBP-3R by IGFBP-3 and IGFBP-3R agonistic mAb inhibits cell growth by inducing apoptosis and by tumor-induced NF-κB activity specifically in cancer cells, but not in normal cells." (PMID 32443727, 2020). "We finally obtained a list of only five genes (AGXT; ALDOB; CYP2E1; IGFBP3; TOP2A) that were differentially expressed in tumor and nontumor tissues across studies and were significantly correlated to HCC prognosis." (PMID 31771612, 2019). "IGFBP3 also displays intrinsic activity, independent of IGF1, and has been reported to be involved in tumor development and progression by regulating cell growth and apoptosis." (PMID 29947889, 2018). "Our data on phospho-AKT, and a lack of normal down-regulation of Igfbp3 expression, suggest that there is constitutive IGF activity in the tumors that lost Ng2/Cspg4 at tumor initiation." (PMID 29196603, 2018). "Mice lacking IGFBP-3 were resistant to HFD-induced weight gain – observed from week 12-13, before tumor cell implantation – and showed reduced tumor growth." (PMID 27448965, 2016). "Tumor growth of MCF7/HER2 xenografts was not inhibited by single-agent trastuzumab, whereas single-agent IGFBP3 showed a trend toward growth inhibition." (PMID 22830017, 2012). "Our previous findings also showed a substantial upregulation of IGFBP3 in both α-SMA-expressing stromal cells and tumor cells; unfortunately, expression levels of IGF2 could not be evaluated in that study as it was not included within the analysis panel." (PMID 40522948, 2025). "Also, IGFBP-3, one of IGF-1 binding proteins, is thought to have tumor suppressive effects independent of IGF-1, by promoting apoptosis, and inhibiting growth, invasion, and angiogenesis." (PMID 38082056, 2024). "Indeed, molecular studies have shown that IGFBP3 has biological functions that are independent of IGF1, such as involvement in tumor development and progression by mediating DNA damage responses, autophagy and apoptosis." (PMID 29947889, 2018). "However, direct targeting of IGFBP3 as a common TEC-directed therapy may not be straightforward since it appears to have tumor-promoting and anti-tumor effects in different cancers." (PMID 39516665, 2024). "Lambrechts and co-workers classified tumor endothelial cells in different clusters based on the marker genes identified; Lymphatic endothelial cells (PDPN+, PROX1+), tumor-derived blood endothelial cells (FLT1+, IGFBP3+, and SPRY1+), malignant, and non-malignant endothelial cells." (PMID 33763348, 2021).